CTLA4 (cytotoxic T-lymphocyte associated protein 4)
Diseases named in the same sentence as CTLA4 in open-access papers (continued):
Sharing a sentence is not in itself a finding about the gene and the disease.
melanoma (continued). "The FDA has approved various ICIs for advanced melanoma, including the CTLA-4 inhibitor ipilimumab and PD-1 inhibitors such as nivolumab and pembrolizumab." (PMID 39516682, 2024). "For example, combining nivolumab (anti-PD1) with ipilimumab (anti-CTLA4) in melanoma has shown better outcomes than using either drug alone." (PMID 39001539, 2024). "Antibodies against the immune checkpoint receptors, such as programmed cell death protein 1 (PD-1), PD-1 ligand (PD-L1/2), and cytotoxic T-lymphocyte-associated protein 4 (CTLA-4), can be used to counteract the immune checkpoint modulation in melanoma." (PMID 38183141, 2024). "As a consequence, we conducted the TIDE method and subclass mapping to predict melanoma who responded to immune-checkpoint inhibitors (CTLA-4 and PD-1)." (PMID 38475660, 2024). "The CheckMate-238 trial evaluated PD-1 inhibitor nivolumab versus CTLA-4 inhibitor ipilimumab as adjuvant therapy in resected advanced melanoma (stage IIIB, IIIC, and IV)." (PMID 39123418, 2024). "A similar study combining the modified herpes simplex virus talimogene laherparepvec (T-VEC) with CTLA-4 blockade was conducted in a melanoma mouse model, for which an increased efficacy of the combination therapy was reported by the authors." (PMID 38254857, 2024). "Of note, we also studied the association of described genes with response to Ipilimumab (anti-CTLA4 therapy), in melanoma patients." (PMID 38710724, 2024). "Another study explored the role of gut microbiota in the development of irAEs in patients receiving anti-CTLA-4 therapy for melanoma." (PMID 39228005, 2024). "Next, we investigated in vivo cDC1 reprogramming as monotherapy or in combination with either anti-PD-1 or anti-CTLA-4 using B16, B2905 and the additional melanoma model YUMM1.7, which is resistant to ICB and also depends on cDC1 availability." (PMID 39236156, 2024). "In recent years, targeted therapy with BRAF/MEK inhibitors and immunotherapy with PD-1, PD-L1, and CTLA-4 inhibitors have made significant strides in the outcomes and prognosis of melanoma." (PMID 39749047, 2024). "Both CTLA-4 and PD-1 inhibitors are the two types of checkpoint inhibitors currently available to melanoma patients." (PMID 38474231, 2024). "Ipilimumab (the anti-CTLA-4 antibodies) and nivolumab (the anti-PD-1 antibodies) serve as the routine treatment for advanced melanoma nowadays." (PMID 38217549, 2024). "This trial combined autologous DCs pulsed with melanoma-associated antigens (TriMixDC-MEL) and the CTLA-4-blocking antibody Ipilimumab." (PMID 39062753, 2024). "Specifically, anti-PD-1 and/or anti-CTLA-4 have been proved to increase the overall survival (OS) of patients with melanoma." (PMID 38612436, 2024). "In another cohort of melanoma patients who received anti-CTLA4 or anti-CTLA4 + anti-PD1 therapy (n = 35), Hypo-MS4 was consistently associated with poor responses but was less significant (P = 0.36)." (PMID 38566132, 2024). "A 55-year-old male patient with stage IV melanoma was treated with systemic chemotherapy combined with anti-PD-1 antibody (nivolumab) and anti-CTLA-4 antibody (ipilimumab) treatment." (PMID 38965595, 2024). "In contrast, expression of mLama4MHC-I or mAlg8MHC-I neoAg along with mItgb1MHC-II neoAg rendered YUMM1.7 melanoma lines (Y1.7LI and Y1.7AI) sensitive to anti-CTLA-4 ICT." (PMID 39446585, 2024). "Anti-CTLA4 immunotherapy can significantly deplete CD68 macrophage in patients with advanced melanoma compared to the untreated sample group." (PMID 39499374, 2024). "Anti-programmed death 1 (PD-1) antibodies, either alone or in combination with an anti-cytotoxic T lymphocyte-associated antigen-4 (CTLA-4) antibody, have been used in the treatment of BRAF-mutant melanoma." (PMID 39336897, 2024).
melanoma (continued). "As an example, the combination therapy of immune checkpoint inhibitors, particularly the administration of both anti-CTLA-4 and anti-PD-1 agents (ipilimumab and nivolumab), yields the highest 5-year overall survival rates in advanced melanoma." (PMID 38891988, 2024). "In parallel, PD-1/PD-L1 and CTLA-4 inhibitors have significantly impacted the treatment landscape of melanoma, particularly in advanced stages." (PMID 39582535, 2024). "In 2011, ipilimumab, a human monoclonal cytotoxic T-lymphocyte-associated protein 4 (CTLA-4) antibody, was the first immune checkpoint inhibitor (ICI) approved for use in patients with metastatic or unresectable melanoma." (PMID 38952584, 2024). "A phase III trial demonstrated the superiority of TILs over ipilimumab (anti-CTLA-4) in patients with PD-1-resistant melanoma, with an improvement in median PFS from 3.1 to 7.2 months and median OS from 18.9 to 25.8 months." (PMID 39508576, 2024). "While both CTLA-4 and PD-1 mAbs have resulted in increased patient survival in numerous cancer types such as melanoma or non-small cell lung cancer (NSCLC), ICI still include important limitations." (PMID 38318190, 2024). "Melanoma patients treated with anti-CTLA-4 and anti-PD-1 mAbs who developed immune-related enterocolitis had a better clinical response and OS compared to subjects who developed other adverse events (AEs)." (PMID 39126091, 2024). "Stimulating the Flt3/Flt3L axis with anti-CTLA-4 improved outcomes in the B16 melanoma and TRAMP prostate adenocarcinoma mouse models." (PMID 38261139, 2024). "High levels of TMB have been shown to correlate with increased responsiveness of non-small-cell lung cancer to immune checkpoint inhibitors nivolumab and ipilimumab and of malignant melanoma to anti-CTLA-4 antibody treatment." (PMID 39347330, 2024). "A clinical trial exploring the addition of sargramostim to CTLA-4 inhibition combined with PD-1 inhibition in melanoma is ongoing (ECOG-ACRIN6141; NCT02339571)." (PMID 38339253, 2024). "Among the more studied immune checkpoint axes being targeted for enhanced melanoma cell killing are the cytotoxic T-lymphocyte antigen 4 (CTLA-4) axis and programmed cell death protein 1 (PD-1) with programmed death-ligand 1 (PD-L1) axis." (PMID 39682188, 2024). "This was similar to the previous findings on melanoma patients treated with anti-CTLA-4 inhibitors, where bacterial metabolism pathways involved in B vitamin biosynthesis were indicated to protect patients from immune-related colitis." (PMID 38243343, 2024). "While PD-1/PD-L1 and CTLA-4 inhibitors have revolutionized melanoma treatment, challenges such as resistance necessitate exploring alternative and combinatorial therapies." (PMID 39582535, 2024). "Another study of advanced melanoma patients treated with combined CTLA-4 and PD-1 blockade (n = 40) found that responders had enriched levels of Bacteroides stercoris, Parabacteroides distasonis, and Fournierella massiliensis." (PMID 39840031, 2024). "Anti-PD-1 and Anti-CTLA-4 immunotherapies inhibit these targets and prevent melanoma cells from evading the immune system." (PMID 38594730, 2024). "For example, anti-PD-1/L1 therapy combined with anti-CTLA4 has become the standard for the treatment of melanoma, and the combination of nivolumab and ipilimumab in patients with advanced melanoma can improve the survival rate of patients of 5 years." (PMID 38697964, 2024). "It is more frequently observed in patients with melanoma treated with anti-CTLA4 drugs (2–9%), anti-PD-L1 (7–11%), or combinations, while it is less frequent in patients treated with ICIs for other tumors." (PMID 38611115, 2024). "The first FDA-approved drug to block immune checkpoints was the human anti-CTLA-4 monoclonal antibody, ipilimumab, used for the treatment of melanoma (CTLA-4—a co-inhibitor that inhibits T cell activation)." (PMID 39769334, 2024).
melanoma (continued). "TILs are particularly significant in melanoma, where they have been shown to predict response to immune checkpoint inhibitors such as anti-PD-1 and anti-CTLA-4 therapies." (PMID 39583615, 2024). "The classic combination of ipilimumab (anti-CTLA-4) plus nivolumab (anti-PD-1) has shown clinically meaningful successes in a variety of advanced solid tumors, including melanoma, NSCLC, HCC, renal cell carcinoma, and colorectal cancer." (PMID 38310192, 2024). "Recently, a retrospective study investigated the efficacy and safety of regorafenib, a multitargeted kinase inhibitor, in 27 advanced melanoma patients who had previously progressed on anti-PD-1, anti-CTLA-4, and BRAFi/MEKi." (PMID 39582535, 2024). "The standard of care for patients with melanoma is combination blockade of CTLA-4 and PD-1 and results in a 5-year overall survival of approximately 60%." (PMID 39436696, 2024). "On the other hand, the combination of ipilimumab (anti-CTLA-4) and nivolumab (anti-PD-1) significantly increases the response of about 60% of melanoma patients compared with monotherapy or chemotherapy." (PMID 38914547, 2024). "Metastatic melanoma burden in the lungs was significantly reduced by anti‐PD‐1 and anti‐CTLA‐4 treatment, which was comparable to the protection afforded by HPK1 deficiency alone." (PMID 38828677, 2024). "The immunotherapeutic response in a cohort of PRJEB23709, the response group proved the higher LAMP3 expression level in LAMP3 with anti‐PD‐1 monotherapy and anti‐PD‐1/anti‐CTLA‐4 combined therapy in melanoma (p < 0.05)." (PMID 38146591, 2024). "Although higher Treg presence in melanoma patients is generally associated with a poor prognosis, the effect of ICI treatment on this CD4+ subtype appears to differ between anti-CTLA-4 and anti-PD-1." (PMID 39273452, 2024). "Ipilimumab (an anti-CTLA4 agent) plus nivolumab also demonstrated a less favorable safety profile in patients with advanced melanoma than fianlimab plus cemiplimab in the present study." (PMID 39422598, 2024). "Two studies on melanoma switched from a PD-1 antibody to a CTLA-4 antibody during immunotherapy rechallenge." (PMID 39726701, 2024). "The FDA previously approved several ICIs targeting CTLA-4, including the mAb ipilimumab for melanoma worldwide and renal cell carcinoma in the US and tremelimumab for diverse types of cancers." (PMID 38791528, 2024). "The therapeutic anti-CTLA-4 antibody, ipilimumab, initially had success in treating melanoma and has now been approved for the treatment of multiple cancers." (PMID 39104861, 2024). "In this study, we combined analyses of the tumor immune microenvironment and tumor intrinsic features on human melanoma specimens taken at progression from patients receiving PD1 or CTLA4 blockade monotherapy." (PMID 38594286, 2024). "Clinical advances: CTLA4 inhibitors, such as ipilimumab, have established efficacy in melanoma, with a reported 5-year survival rate of 18.2%." (PMID 38713378, 2024). "The application of ipilimumab (anti-CTLA-4) in a combinatory therapy for stage III/IV melanoma patients was a historical step towards their introduction in cancer therapy." (PMID 38275902, 2024). "Consistent with previous results, multiple distinct cohorts of melanoma patients who received anti-PD-1, anti-CTLA-4, or combined therapy showed that Bacteroidaceae species have a negative correlation with responsiveness." (PMID 38547865, 2024). "Another potential application of IL-2 therapy that has emerged recently is employing IL-2 as a neoadjuvant to treat malignant melanoma in combination with immune checkpoint inhibitor therapies such as anti-CTLA4 and anti-PD1." (PMID 39682188, 2024). "A phase 1 clinical trial evaluated the efficacy of locally administering anti-CTLA-4 into TDLNs in patients with stage I/II melanoma (NCT04274816)." (PMID 39211044, 2024).
melanoma (continued). "Melanoma was the first cancer where ICBs were approved, with the anti-CTLA-4 monoclonal antibody (mAb) ipilimumab demonstrating a significant increased overall survival (OS) versus standard treatments." (PMID 38843391, 2024). "In this study, we evaluated the antitumor effects of local CpG-Stat3 siRNA treatment at tumor sites to boost the antitumor effects of CTLA4 and/or PD-1 antibody systemic treatments in the A20 mouse lymphoma model and the B16 melanoma model." (PMID 39618825, 2024). "Subtypes in melanoma against PD1 survival benefit of anti‐CTLA4 therapy in studies suggesting biological subtypes used as independent predictive markers to aid clinical decision making." (PMID 39663596, 2024). "The dysregulation of immune checkpoint receptors, such as PD-1 and CTLA-4, is a critical mechanism by which melanoma escapes the immune system." (PMID 39026661, 2024). "The CpG oligonucleotide TLR9 ODN 1826 agonist has been shown to effectively augment the therapeutic potential of checkpoint blockade through locally delivered ODN 1826 and systemic CTLA4 or PD-1 blockade antibody in the B16 melanoma mouse model." (PMID 39618825, 2024). "Ipilimumab, the first FDA-approved CTLA-4 blocker for melanoma, is commonly used in CRC treatment as an adjunctive or rescue therapy." (PMID 39839672, 2024). "The first ICI mAb to receive an FDA approval was ipilimumab (anti-CTLA-4 mAb) in 2011 for the treatment of advanced stage melanoma." (PMID 38318190, 2024). "Clinical data show that 20–40% of melanoma patients respond to these monotherapies, whereas around 60% of patients respond to treatment with a combination of CTLA4 and PD-1 blockers." (PMID 39000359, 2024). "The relationship between LAMP3 and the response to anti‐PD‐1 monotherapy and anti‐PD‐1/anti‐CTLA‐4 combined therapy in melanoma patients showed that the survival of patients with high LAMP3 expression was better than those with low LAMP3 expression (p < 0.05)." (PMID 38146591, 2024). "Consistent with prior observations, the parental YUMM1.7 melanoma line was insensitive to anti-CTLA-4 and/or anti-PD-1 ICT." (PMID 38187708, 2024). "Ipilimumab was the first anti‐CTLA‐4 monoclonal antibody (mAb) approved for human use in 2011 for the treatment of late‐stage melanoma that was difficult to treat with surgery." (PMID 38894611, 2024). "Using the genomic profiles of melanoma samples treated with anti‐CTLA4 (Van Allen cohort), we classified these samples into three groups according to the mutation signature obtained by TCGA data." (PMID 39323009, 2024). "It is indicative that CYTlow melanomas downregulate the expression of several immune checkpoints, including CTLA-4 and PD-1." (PMID 38612436, 2024). "Similar findings were observed in a group of advanced melanoma patients who received combination anti-PD-1 and anti-CTLA-4." (PMID 38261139, 2024). "Some clinical trials and studies have shown that the combined use of nivolumab (a PD-1 inhibitor) and ipilimumab (a CTLA-4 blocker) is more effective for patients with advanced melanoma." (PMID 38807592, 2024). "Local delivery of low-dose anti–CTLA-4 has been proposed to reduce toxicity while maintaining efficacy, such as recently shown for local delivery to the lymphatic basin in melanoma." (PMID 39485838, 2024). "Targeted therapies involving BRAF/MEK inhibitors and immunotherapy based on anti-PD1/anti-CTLA4 antibodies have achieved long-term survival rates of approximately 50% for patients with advanced melanoma." (PMID 38336727, 2024). "In contrast, miR-4649-3p and miR-615-3p overexpression was observed in stage IV melanoma patients who progressed after anti-CTLA-4 (Ipilimumab), anti-PD-1 (Nivolumab or Pembrolizumab), or the combination of Ipilimumab and Nivolumab." (PMID 38339019, 2024). "Although immunotherapy with combination anti-PD-1 and anti-CTLA-4 delivers durable responses in melanoma patients, half of the patient population demonstrates resistance, either intrinsically or acquired." (PMID 39491031, 2024).
melanoma (continued). "The FDA has approved the CTLA-4 inhibitor ipilimumab for adjuvant therapy in stage III melanoma and advanced melanoma." (PMID 39080807, 2024). "Studies dedicated to melanoma treatment report response rates of 20% for anti-CTLA-4 and 40% for anti-PD-1, accompanied by 5-year progression-free survival (PFS) rates of 8% and 20%, respectively." (PMID 39435293, 2024). "Here, we show that the modulation of CD4+FOXP3+CD25+regulatory T (Treg) cells upon anti-CTLA4 treatment protects against lymphedema development in patients with melanoma and in a mouse lymphedema model." (PMID 39737964, 2024). "Conversely, combining CTLA-4 inhibitors with IL-6 inhibitors enhances the tumor microenvironment in malignant melanoma, leading to a significant reduction in tumor size and improved survival in mice." (PMID 39703501, 2024). "The Keynote-006 randomized phase 3 study serves as a crucial evaluation comparing pembrolizumab, a PD-1 blocker, against ipilimumab, an inhibitor of the CTLA-4 immune checkpoint, in the treatment of advanced melanoma." (PMID 39155358, 2024). "This has been confirmed in clinical settings, where combined therapy using ipilimumab (CTLA-4 antibody) and nivolumab (PD-1 antibody) has demonstrated greater efficacy than monotherapy in treating advanced melanoma." (PMID 38500876, 2024). "Peripheral blood samples were analyzed from patients with melanoma treated with anti-PD-1 monotherapy or anti-PD-1 and anti-CTLA-4 combination." (PMID 38672249, 2024). "In prior studies, we demonstrated synergistic increased tumor protection with the concurrent activation of the ICOS pathway and CTLA-4 blockade in mouse melanoma and prostate cancer models." (PMID 38517331, 2024). "This reaction is accompanied by hypermethylated endogenous retrovirus (ERV) genes, and in patients with melanoma receiving immune checkpoint therapy—specifically, anti-CTLA4—the viral defense signature is correlated with a long-lasting clinical response." (PMID 38931856, 2024). "Ipilimumab was approved for melanoma in 2013 and functions as an anti-CTLA-4 monoclonal antibody blocking downstream signaling and resulting in a more robust and prolonged T-cell-mediated immunity against melanoma tumor cells." (PMID 38956559, 2024). "When challenged with B16 melanoma and treated with anti-PD-1/anti-CTLA-4 immune checkpoint blockade (ICB), lean mice on NC resisted tumor progression whereas obese mice on WD showed no therapeutic response." (PMID 38565540, 2024). "It should be noted that some melanoma patients receive combination treatments with anti-CTLA-4 and anti-PD-1 mAbs, and yet almost 50% of them show negligible responses." (PMID 39474427, 2024). "Further, studies in both preclinical models and human melanoma patients have revealed that anti-CTLA-4 induces ICOS+ CD4 T cells expressing IFN-γ78,79." (PMID 38187708, 2024). "In the examination of transcriptome sequencing data before and after treatment with nivolumab (PD-1/CTLA-4 antibodies) in 105 advanced melanoma patients, those who responded to the therapy (23 cases) showed significantly higher GZMK expression (P < 0.05)." (PMID 38833021, 2024). "In contrast, enforced expression of mLama4MHC-I or mAlg8MHC-I NeoAg along with mItgb1MHC-II NeoAg rendered YUMM1.7 melanoma lines (Y1.7LI and Y1.7AI) sensitive to anti-CTLA-4 ICT." (PMID 38187708, 2024). "As a crucial immune checkpoint, the cytotoxic T-lymphocyte-associated antigen 4 (CTLA-4) blockade Ab has demonstrated encouraging anti-tumor effects in various cancers, including lung cancer, melanoma, and colon cancer." (PMID 38398223, 2024). "Across various cancers, like melanoma, colorectal cancer, and lung cancer, immune checkpoint inhibitors including anti-PD-1/PD-L1, anti-CTLA-4, and anti-Tim3, has significantly enhanced progression-free and overall survival rates." (PMID 39421747, 2024). "And it was also identified as a favorable prognostic marker in melanoma patients receiving CTLA-4 therapy." (PMID 38720348, 2024).